C6orf132 (chromosome 6 open reading frame 132)
Synonyms: bA7K24.2; LncCCLM
Tractability: No criterion of Open Targets' tractability assessment is met for any kind of drug.
Gene: Protein-coding gene on chromosome 6 (42,092,233 to 42,142,620, reverse strand). Ensembl gene ENSG00000188112.
Subcellular location (Human Protein Atlas): Cytosol; Golgi apparatus
Genetic constraint (gnomAD): Loss-of-function variants: 38 observed, 57.6 expected, observed/expected ratio (o/e) 0.66, 90% interval 0.51 to 0.87. The upper end of that interval is the gene's LOEUF score, 0.87, which puts it in group 3 of 6, group 1 being the genes least tolerant of losing a copy. Missense variants: 1,354 observed, 1,392.6 expected, observed/expected ratio (o/e) 0.97, 90% interval 0.93 to 1.02. Synonymous variants: 569 observed, 582.8 expected, observed/expected ratio (o/e) 0.98, 90% interval 0.91 to 1.05.
Homologues: Orthologues: chimpanzee C6H6orf132 (98% identical), macaque C4H6orf132 (93% identical), pig C6orf132 (72% identical), mouse AI661453 (69% identical), dog C6orf132 (68% identical), rat C9h6orf132 (67% identical), rabbit C6orf132 (66% identical).
Diseases named in the same sentence as C6orf132 in open-access papers:
C6orf132 is named in the same sentence as 4 diseases in open-access papers, as found by Europe PMC text mining. Sharing a sentence is not in itself a finding about the gene and the disease. The quoted sentences say what the papers report.
sarcoidosis (1 paper, 2025). Sarcoidosis is a multisystemic disorder of unknown cause characterized by the formation of immune granulomas in involved organs. "The most increased proteins in sarcoidosis were uncharacterized protein C6orf132 (Q5T0Z8, log2FC, 1.7 and −log10P, 11) and zinc finger protein 607 (Q96SK3, log2FC, 2.5 and −log10P, 7.0)." (PMID 41279897, 2025).
testicular germ cell tumor (1 paper, 2023). A germ cell tumor arising from the testis. "Thus, 124 out of 219 genes are down-regulated in testicular germ cell tumor (TGCT), except for one up-regulated (C6orf132), and 100 out of them are down-regulated in TGCT only (mentioned here, ‘TGCT-specific 100-gene expression signature’)." (PMID 37373333, 2023).
C6orf132 also shares sentences with these, for which no sentence is quoted: cancer (1 paper); thymoma (1).